EP300 (EP300 lysine acetyltransferase)
Diseases named in the same sentence as EP300 in open-access papers (continued):
Sharing a sentence is not in itself a finding about the gene and the disease.
hepatocellular carcinoma (43 papers, 2011 to 2025). A malignant tumor that arises from hepatocytes. "EIF4A3 and E1A binding protein p300 (EP300) synergistically promote the biogenesis of circCCAR1 in hepatocellular carcinoma." (PMID 39550559, 2024). "EP300-mediated H3-K27ac also promotes the biogenesis of circCCAR1 in hepatocellular carcinoma cells." (PMID 39550559, 2024). "EP300 gene is amplified or gained in approximately 24% of human hepatocellular carcinoma tissues, and EP300 gene over-expression positively correlates with the gene copy number variations and poor patient prognosis." (PMID 35836809, 2022). "Previous studies suggest that high expression of the transcriptional coactivator EP300 correlates with aggressive features of hepatocellular carcinoma and cutaneous squamous cell carcinoma." (PMID 34149798, 2021). "EP300 knockdown strongly increased E-Cadherin expression and significantly decreased migration and invasion in a hepatoma cell line (HLE) that is otherwise highly invasive and poorly differentiated." (PMID 25883651, 2015). "In addition, previous data have detected loss of heterozygosity at the EP300 or CREBBP loci in colorectal, gastric, ovarian, and hepatocellular carcinomas." (PMID 32493417, 2020). "Moreover, hepatocellular carcinoma and PCa with gain of HLA, PSMB, and TAP genes, possibly due to chromosome 6p amplification, show higher frequency of CBP/EP300 loss, which may allow them to undergo immune evasion." (PMID 33602823, 2021). "In support of this, elevated expression of EP300 in hepatocellular carcinomas (HCC) correlates with enhanced vascular invasion, intrahepatic metastasis, shortened survival, and, strikingly, low E-Cadherin expression." (PMID 25883651, 2015). "For those of normal weight, the hepatitis B pathway, composed of RB1, EP300, PIK3CB, HSPG2 and JAK1 (K = 9), may serve as a key point for effective treatment and prevention, because chronic infection with hepatitis viruses is a major causative factor for hepatocellular carcinoma." (PMID 40768543, 2025). "Further experimentation revealed that in hepatocellular carcinoma, MYC/MAX and EP300 activate PPM1G which in turn dephosphorylates SRSF3, triggering the alternative splicing of genes related to cell cycle and transcriptional regulation." (PMID 37953273, 2023).
cardiac hypertrophy (42 papers, 2012 to 2025). "FOS and JUN transcription factors are thought to be among the first set of genes to be expressed in the context of pathological cardiac hypertrophy, and EP300 has been associated with cardiomyocyte enlargement." (PMID 28797094, 2017). "We also examined genes that are not transcriptionally regulated via PPAR α, but tend to alter in cardiac hypertrophy (PRKAG2 and EP300)." (PMID 35224041, 2022).
diabetes (40 papers, 2011 to 2026). "Alterations in EP300 expression or mutations in the EP300 gene are closely related to the occurrence and development of diabetes." (PMID 40508108, 2025). "EP300 (ranked at 13, aliases p300), as a transcriptional coactivator, could cause diabetes via regulating fibronectin expression via PARP and NF-kappaB activation." (PMID 21799737, 2011). "Due to the diverse roles of EP300 in diabetes pathogenesis, further studies are needed to elucidate its phenotypic and functional characteristics under pathological conditions." (PMID 40508108, 2025). "The increase in EP300 and decrease in miR-133a mRNA levels following diabetes were normalized to control levels in miR-133a TG diabetic mice." (PMID 24428157, 2014). "In this study of STZ-induced diabetes, we observed that diabetes increased EP300 mRNA levels concurrent with a decrease in miR-133a in the heart suggesting a possible negative regulation of miR-133a in diabetes." (PMID 24428157, 2014). "Recent studies have proposed that Ep300 may play an important role in diabetes-related inflammation and oxidative stress through epigenetic mechanisms and transcription factor acetylation." (PMID 40508108, 2025). "Cardiac miR-133a overexpression in diabetes inhibits EP300, preventing early cardiac fibrosis." (PMID 33995494, 2021). "Glucose uptake can fuel glycolysis to generate acetyl-CoA, a key co-factor for the EP300/CBP acetyl transferase that should be important for several pathologies, including diabetes and cancer." (PMID 32603375, 2020). "In order to verify whether ESR1, EP300, NFKB1, and HDAC1 are relevant in ginsenoside treatment of diabetes, Western blot analysis was performed on pancreatic tissue from STZ-induced T1DM mice treated with AD-1." (PMID 40508108, 2025).
acute myeloid leukemia (39 papers, 2002 to 2025). Acute myeloid leukemia (AML) is a group of neoplasms arising from precursor cells committed to the myeloid cell-line differentiation. "For example, small molecules that disrupt the EP300–MYB interaction inhibit acute myeloid leukemia (AML) cell proliferation both in vitro and in vivo." (PMID 40558489, 2025). "Other fusion genes involved EP300, ZNF384 and dozens of other genes have been reported in acute myeloid leukemia (AML) and B-ALL." (PMID 32980888, 2020). "Indeed P300 (also known as EP300) and CBP are fused to MLL in acute myeloid leukaemia." (PMID 12402157, 2002). "In addition, several recently developed EP300/CREBBP bromodomain inhibitors have been reported to mediate antiproliferative responses in hematologic cancer cell lines, such as acute myeloid leukemia (AML) and multiple myeloma cell lines and AR-positive prostate cancer cell lines." (PMID 29884215, 2018).
colon carcinoma (39 papers, 2006 to 2025). "Initial work showsthat inhibition of the CREBBP/EP300 bromodomain results in the downregulationof c-Myc in HCT116 colon cancer cells." (PMID 34255515, 2021). "In support of a ROS/AMPK/EP300/β-catenin axis mediating glucose-induced proliferation of colon cancer cells, blockade at each level abolished the effects of glucose on proliferation." (PMID 32603375, 2020). "HCT116 colon carcinoma cells are hemizygous for EP300 and due to the high frequency of homologous recombination in these cells, an EP300 genetic knocked-out model showing characteristics of EMT, has previously been generated." (PMID 28341962, 2017). "We used lentiviruses expressing EP300-targeting shRNA to downregulate its expression in MCF-7 cells as well as an EP300-knocked-out colon carcinoma cell line." (PMID 28341962, 2017). "We have validated at least two examples (CREBBP and EP300) of naturally expressed mutant proteins in MSI-High colon cancer cell lines, both arising from NMD-resistant transcripts." (PMID 21209843, 2010). "Indeed, inhibition of protein synthesis by cycloheximide (CHX) revealed augmented EP300 protein stability in HCT 116 colon cancer cells exposed to glucose, likely triggered by PTMs." (PMID 32603375, 2020). "Importantly, two key genes in apoptosis and stemness, BCL2 and ABCG2, were also upregulated in EP300-knockout colon carcinoma cells and their paclitaxel-resistant derivatives." (PMID 28341962, 2017). "Importantly, this increase in paclitaxel resistance was also reproduced in EP300-knocked-out colon carcinoma HCT116 cells with an IC50 increase of 4.6-fold." (PMID 28341962, 2017).
pancreatic cancer (35 papers, 2016 to 2026). "The occurrence of the EP300 gene mutation in pancreatic cancer is a hint towards its tumor-suppressive function." (PMID 37659057, 2023). "PORCN inhibitor–resistant RNF43-mutant pancreatic cancer cell lines harbor loss-of-function genetic alterations in EP300." (PMID 35536676, 2022). "While genetic alterations in EP300 occur in less than 2% of treatment-naive pancreatic tumors, cooccurrence of EP300 and RNF43 mutations has been observed in resected pancreatic tumors." (PMID 35536676, 2022). "EP300 gene has often been found to be mutated/truncated in lymphomas and different solid tumors, such as gastric, colorectal, breast, and pancreatic cancers, and over-expressed and correlated to poor prognosis in liver, nasopharyngeal, and small and non-small cell lung cancer." (PMID 32933107, 2020). "Previous studies have demonstrated that EP300‐mediated HSPA5 acetylation at K353 enhances resistance in pancreatic cancer cells, whereas dihydroartemisinin‐induced ERS mitigates iron death in glioma cells through the PERK/ATF 4/HSPA5 pathway." (PMID 40371728, 2025). "This bioinformatics analysis found that the expression of EP300 in pancreatic cancer tissues was higher than that in normal adjacent tissues." (PMID 37696842, 2023). "In a recent study, it was found that mutations in EP300 lead to resistance against inhibitors of porcupine (PORCN), an endoplasmic reticulum O-acyltransferase, in RNF43-mutant pancreatic cancers." (PMID 37659057, 2023). "Supporting its importance, we found that EP300 is inactivated in the preexisting PORCN inhibitor–resistant RNF43-mutant pancreatic cancer cell lines." (PMID 35536676, 2022). "This pattern was also seen when we compared the existing RNF43/EP300-mutant pancreatic cancer cell lines with the EP300-WT cell lines." (PMID 35536676, 2022). "We found that EP300 is silenced due to genetic alterations in all the existing RNF43-mutant pancreatic cancer cell lines that are resistant to PORCN inhibitors." (PMID 35536676, 2022). "Even, down-regulation of EP300 impaired E2F1-mediated activation of the VMP1 promoter in pancreatic tumor cells." (PMID 32655498, 2020). "Two components of the Notch signaling pathway, ADAM17 and EP300, were confirmed as miR-148a targets in MiaPaca-2 pancreatic cancer cells overexpressing miR-148a." (PMID 29464088, 2018). "Notably, GATA6 protein abundance was also markedly reduced in the RNF43/EP300-mutant pancreatic cancer cell lines, and reexpressing p300 in EP300-mutant PL45 cells upregulated GATA6 expression." (PMID 35536676, 2022). "We further investigated whether reexpressing WT EP300 in the existing RNF43/EP300-mutant pancreatic cancer cell line was able to rescue the Wnt dependency." (PMID 35536676, 2022). "We measured the expression of key members of the Notch Signaling Pathway (NUMB, DTX4, DTX3L, PSEN1, APH1A, ADAM17 and EP300) in the MiaPaCa-2-miR-148a by qRT-PCR, and compared it with the basal levels of the control pancreatic cancer cell line MiaPaCa-2, expressing very low levels of miR-148a." (PMID 29464088, 2018). "Notably, given that the frequency of genetic alterations in EP300 is less than 2% in treatment-naive pancreatic tumors, there are likely to be additional mechanisms regulating GATA6 expression in basal-like tumors that may be dependent or independent of p300." (PMID 35536676, 2022). "Mechanistically, loss of EP300 directly downregulated GATA6 expression, thereby silencing the GATA6-regulated differentiation program and leading to a phenotypic transition from the classical subtype to the dedifferentiated basal-like/squamous subtype of pancreatic cancer." (PMID 35536676, 2022). "However, only miR-103 was directly involved in the regulation of pancreatic cancer-associated processes: E-cadherin signalling events (CDH1), TGF beta signalling pathway (TGFBR2, APC, CDH1, CREBBP, EP300, SMAD3, TSC2), and altered TFG-beta SMAD dependent signalling (TGFBR2, SMAD3, and FBXW7)." (PMID 29285254, 2017).
pancreatic cancer (continued). "Notably, epigenetic modifiers frequently showed more mutations in AYAs, including H3F3A, KDM5A and IDH1/2 in glioma, EP300 in liver cancer, SMARCA4 in ovarian cancer, and MEN1 in pancreatic cancer." (PMID 36433963, 2022). "In this study we have confirmed the involvement of miR-148a-ADAM17, miR-148a-EP300, miR-21-PDCD4 and miR-21-BTG2 interactions in the pancreatic cancer cell with the help of genetically modified pancreatic cancer cellular models (stable overexpression or CRISPR/Cas9 knock-out, respectively)." (PMID 29464088, 2018).
Rubinstein-Taybi syndrome (35 papers, 2009 to 2025). A rare malformation syndrome characterized by congenital anomalies (microcephaly, specific facial characteristics, broad thumbs and halluces and postnatal growth retardation), short stature, intellectual disability and behavioral characteristics. "Variants elsewhere in CREBBP and EP300 result in Rubinstein-Taybi syndrome (RSTS1, OMIM # 180849 and RSTS2, OMIM# 613684), which is largely phenotypically distinct." (PMID 40860344, 2025). "This patient also showed a heterozygous null variant, EP300 (NM_001429.4): c.4261dup (p.Tyr1421Leufs∗22); associated with Rubinstein-Taybi syndrome (RSTS), a novel pathogenic variant as per ACMG guidelines." (PMID 39263390, 2024). "Patients carrying autosomal dominant mutations in the histone/lysine acetyl transferases CBP or EP300 develop a neurodevelopmental disorder: Rubinstein-Taybi syndrome (RSTS)." (PMID 36385105, 2022). "Rubinstein-Taybi syndrome (RSTS) is a rare neurodevelopmental disorder caused by mutations in CREBBP or EP300 genes encoding CBP/p300 lysine acetyltransferases." (PMID 34071322, 2021). "Mutations in CREBBP (cAMP-responsive element binding protein (CREB) binding protein) and in EP300 (e1a-binding protein p300) cause Rubinstein Taybi syndrome (RTS: OMIM 180849)." (PMID 19721813, 2009). "Rubinstein-Taybi syndrome (RSTS) is a rare multisystem developmental disorder with moderate to severe intellectual disability caused by heterozygous mutations of either CREBBP or EP300 genes encoding CBP/p300 chromatin regulators." (PMID 32562237, 2020). "Defects of EP300 can cause Rubinstein-Taybi syndrome (a disease with short stature and intellectual disability) and may result in the formation of tumors." (PMID 30323833, 2018). "Including the two newly reported cases in this study, a total of 8 Chinese patients with Rubinstein-Taybi syndrome (RSTS) caused by EP300 gene variants were included." (PMID 40672389, 2025). "Mutations in CREBBP and EP300 are causative for Rubinstein-Taybi syndrome (RSTS, OMIM 180849 and 613684)." (PMID 26171964, 2015). "The bioinformatic analysis specifically focused on the EP300 and CREBBP genes, which are commonly implicated in Rubinstein-Taybi syndrome (MIM #613684)." (PMID 40692712, 2025). "ADSL deficiency is known to cause epilepsy or autistic features among other characteristics, and EP300 is known to play a role in Rubinstein-Taybi syndrome which includes features overlapping with PMS (e." (PMID 34228749, 2021). "In fact, EP300, together with its paralogous CREBBP, is a gene whose variants are causative of Rubinstein Taybi syndrome by a mechanism of haploinsufficiency." (PMID 33337535, 2021). "In the brain, this gene and its paralog, EP300, are altered in patients with Rubinstein-Taybi syndrome, a rare sporadic neurodevelopmental disorder characterized by neurocognitive deficits, autism-spectrum type behaviors and gross anatomical abnormalities including facial dysmorphism." (PMID 32493417, 2020). "Here we report a patient with initial diagnosis of Rubinstein-Taybi syndrome (RSTS, OMIM #180849, #613684), another chromatinopathy which causative genes CREBBP or EP300 encode for two HATs." (PMID 38753158, 2024). "There are two types of Rubinstein-Taybi syndrome (RSTS): Type 1, which is caused by mutations of the CREBBP gene; and Type 2, which is caused by mutations of the EP300 gene." (PMID 30635043, 2019). "While these results are exploratory, if replicated, there could be a case for reconsidering the comment in the recent consensus guideline for Rubinstein-Taybi syndrome, which stated that there is no increased risk of premature birth for individuals with variants in EP300." (PMID 41168876, 2025).
Rubinstein-Taybi syndrome (continued). "Over the last 20 years, mutations in five key COMPASS complex genes have been linked to three human congenital syndromes: Kabuki syndrome (type 1 [KMT2D] and 2 [KDM6A]), Rubinstein-Taybi syndrome (type 1 [CBP] and 2 [EP300]), and Kleefstra syndrome type 2 (KMT2C)." (PMID 31924266, 2020). "As a congenital multisystemic disorder sharing some similar clinical features with CdLS, Rubinstein-Taybi syndrome (RSTS;OMIM180849,613,684) arises from dysfunction in cyclic-AMP-regulated enhancer binding protein (CREBBP) and E1A binding protein p300 (EP300) as transcriptional co-activators." (PMID 30770747, 2019). "Rubinstein-Taybi syndrome (RSTS) is characterized by distinctive facial features, broad and often angulated thumbs and halluces, short stature, and moderate-to-severe intellectual disability, classified into two types RSTS1 (CREBBP-RSTS) and RSTS2 (EP300-RSTS)." (PMID 37085840, 2023).